LEP (leptin)
Diseases named in the same sentence as LEP in open-access papers (continued):
Sharing a sentence is not in itself a finding about the gene and the disease.
Obesity (continued). "Here, we tested associations of maternal obesity (primary exposures: BMI, leptin) and metabolic parameters (secondary exposures: glucose, C-peptide, and insulin sensitivity) with total serum concentrations of fatty acids in the first trimester of human pregnancy." (PMID 34638763, 2021). "Moreover, overweight and obesity were associated with an increased risk of this disorder, thus suggesting a relationship between leptin and skin diseases such as atopic dermatitis (AD)." (PMID 34827640, 2021). "Thus, we further evaluated mRNAs overlapped among miR-6803-3p-associated mRNAs, predicted miR-6803-3p-related mRNAs, leptin-associated mRNAs, and obesity-associated mRNAs." (PMID 34440082, 2021). "However, a study using a leptin-deficient obesity mouse model and leptin administration revealed an unexpected anti-inflammatory role of leptin." (PMID 34421909, 2021). "Leptin resistance characterized by elevated circulating leptin levels is a hallmark of obesity." (PMID 33808673, 2021). "Conversely, the adiponectin/leptin ratio exhibited differences related with BMI (r = −0.274, p = 0.001), and thus this ratio may be employed as a tool for the assessment of obesity-associated cardiometabolic risk." (PMID 34957187, 2021). "One of the distinct phenotypes of ciliopathy is elevated leptin levels, indicating that leptin resistance may either be a cause or be a consequence of obesity." (PMID 34211092, 2021). "Circulating clusterin is also negatively associated with leptin in obesity-related CVD." (PMID 33717095, 2021). "On the other hand, preservation of leptin signaling mechanisms in the vasculature may be responsible for hyperleptinemia-induced vascular dysfunction associated with obesity and diabetes." (PMID 34064112, 2021). "This study investigated whether Roux-en-Y gastric bypass (RYGB) interacts with obesity-associated hypothalamic inflammation to restore central leptin signaling as a mechanistic account for post-operative appetite suppression." (PMID 33741533, 2021). "Similarly, mice with a polymorphism in the gene encoding LEP-R, display altered leptin signaling that leads to obesity." (PMID 34084149, 2021). "Maternal leptin may also contribute to alower predisposition to diet-induced obesity in the offspringvia food choice, but this issue has beenpoorly studied." (PMID 34782887, 2021). "Shortening of sleep may also affect serum levels of leptin and ghrelin, resulting in increased appetite and reduced energy expenditure, increasing the risk of overweight and obesity." (PMID 33828593, 2021). "Leptin also acts by enhancing the effect of previously outlined obesity-associated biomarkers." (PMID 34944905, 2021). "Obesity is associated with circulating hyperleptinemia as a consequence of leptin resistance, suggesting that obese subjects have resistance to the anorectic and weight-reducing effects of leptin." (PMID 34068919, 2021). "Lower insulin in circulation also prevents leptin-deficient Lep ob/ob mice from developing obesity." (PMID 34032632, 2021). "A GWAS study in Danish, Icelandic, Dutch, European Americans, and African American adults has shown that SNPs in the FTO, MC4R, BDNF, and SH2B1 genes are highly associated with obesity risk via modulating leptin secretion to induce leptin resistance in different ethnicities." (PMID 34836030, 2021). "This change causes a defect in leptin signaling, leading to excessive food intake and an increase in weight and adipose tissue and therefore BMI, which can lead to hyperlipidemia and later obesity." (PMID 34924860, 2021). "Leptin is an important factor driving obesity-associated arterial hypertension." (PMID 34069822, 2021). "However, chronic inflammation, either from autoimmune or infectious diseases, or impaired leptin response to CNS (hypothalamus)/leptin resistance, induce resistance to the weight control, which is a leading cause of obesity and anorexia." (PMID 34220807, 2021). "Most forms of obesity are associated even with leptin resistance." (PMID 34829886, 2021).
Obesity (continued). "The increased adiposity associated with obesity and the redistribution of adipose tissue that occurs during ageing are accompanied by decreased adiponectin concentrations and increased leptin levels, which may reflect leptin resistance." (PMID 34731089, 2021). "Hyperleptinemia, ascribing an elevated leptin level in circulation, is among the diagnostic criteria of hyperlipidemia, hyperglycemia, and hyperinsulinemia (insulin resistance), indicating a metabolic disorder of obesity and associated syndromes." (PMID 34737743, 2021). "Obesity is associated with high levels of circulating leptin combined with leptin resistance." (PMID 34211985, 2021). "Previous studies have shown that obesity may reduce the risk of mortality via the secretion of leptin and soluble TNF receptor 2 during sepsis in adipose tissues." (PMID 34070883, 2021). "As leptin levels are vastly associated with obesity, there is the yet unanswered question of whether leptin alone is responsible for a bad prognosis." (PMID 34220807, 2021). "A global loss of leptin signaling in ob/ob and db/db mice causes obesity and type 2 diabetes, which could contribute to the downregulation of Bdnf mRNA expression in the hippocampus." (PMID 33106599, 2021). "Obesity is associated with increased leptin levels, which induces resistance to chemotherapy." (PMID 33644151, 2021). "Consequently, dysregulation of leptin signaling results in obesity, diabetes, and associated comorbidities." (PMID 34795562, 2021). "However, circulating leptin levels increase under most obesity conditions, and diet-induced obesity is associated with leptin resistance leading to excessive food intake and body weight gain." (PMID 34035808, 2021). "Chronic overnutrition and resulting obesity cause severe derangements in these functions, associated with increased leptin secretion, local inflammation, and release of inflammatory mediators that may negatively affect the function of other tissues." (PMID 33824998, 2021). "Moreover, papain decreased inflammation associated with obesity by inhibiting pro-inflammatory cytokines, leptin, and increased adiponectin through AMPK activation." (PMID 34576066, 2021). "Ad-36 infection in adipocytes reduced leptin production while inducing proliferation, differentiation, and lipid accumulation in adipocytes, suggesting viral infection of fat cells can directly cause adipogenesis and obesity." (PMID 34795562, 2021). "Another molecule implicated in both obesity and depression is leptin." (PMID 33802480, 2021). "While physiological concentrations of leptin may exhibit multiple beneficial effects, chronically elevated pathophysiological levels or hyperleptinemia, characteristic of obesity and diabetes, is a major risk factor for development of atherosclerosis." (PMID 34064112, 2021). "The higher level of pro-inflammatory leptin and lower anti-inflammatory adiponectin ratio could be contributing to the obesity-associated complication due to biased immune response." (PMID 34220807, 2021). "Moreover, leptin can affect the expression of miRNAs in an endocrine manner (e.g., miR-21, miR-27a/b and miR-122) in the liver and, in this way, contribute to obesity-associated liver steatosis (NAFLD) and inflammation (NASH)." (PMID 34943849, 2021). "Although pharmacological administration of leptin dramatically decreases food intake and increases energy expenditure in the rare patients with leptin deficiency, leptin itself has limited potential as an obesity therapeutic." (PMID 34231322, 2021). "Notably, adipose tissues, including BF, have been extensively reported to secrete adiponectin, leptin, resistin, etc., which are associated with skeletal muscle growth, cellular growth, obesity, diabetes, and metabolic diseases." (PMID 34944286, 2021).
Obesity (continued). "Early in life, leptin is believed to stimulate bone growth; however, later in development and during obesity, it may promote bone loss through induction of RANKL expression, thereby promoting osteoclast production and bone reabsorption." (PMID 33554957, 2021). "Leptin is capable of inducing the abnormal proliferation of NP cells, which might be a possible mechanism underlying the impact of obesity in disc degeneration." (PMID 33776562, 2021). "As early as the 1960s, leptin was identified as a hormone linked to obesity." (PMID 34234682, 2021). "Importantly, obesity—through increased production of selected adipokines, e.g., leptin and TNF-α—is associated with low-grade inflammation." (PMID 34063466, 2021). "Furthermore, increased serum leptin levels are probably implicated in the enhanced FGF23 expression in obesity." (PMID 34422722, 2021). "Human obesity is associated with decreased circulating adiponectin and elevated leptin levels." (PMID 33572989, 2021). "Strategies aimed at restoring leptin sensitivity in hypothalamic neurons might represent a hopeful approach for the treatment of obesity and associated comorbidities." (PMID 34208585, 2021). "On the other hand, impaired leptin tolerance elicits metabolic signals that promote energy storage inform of fat deposition and caloric intake, which are crucial features of obesity, thus associating obesity with high leptin concentration." (PMID 34556775, 2021). "Additionally, leptin has been considered a cardiovascular risk factor in individuals with MHO due to its contribution to the inflammatory process related to obesity-associated cardiometabolic complications." (PMID 34099056, 2021). "Our study confirms the hypothesis of a role of leptin in the association between obesity and its related alterations, reporting a factor that may contribute to explain the described differences in the presence of obesity-related alterations by age." (PMID 35071145, 2021). "Ay mice develop obesity-associated hyperleptinemia and leptin resistance; partial restoration of leptin sensitivity in FGF21-treated male mice may contribute to lowering blood insulin levels in males." (PMID 34943946, 2021). "Therefore, leptin treatment is useful for treating obesity, while congenital leptin- or leptin receptor deficiency can lead to hyperphagia and early-onset obesity." (PMID 34684625, 2021). "In addition, H. pylori increase the levels of leptin and ghrelin and predispose people to obesity and diabetes." (PMID 34922625, 2021). "Severe early obesity develops from rare genetic mutations that affect leptin signaling." (PMID 34084149, 2021). "This study shows that maternal leptin may affect taste preferencesin the offspring, and this effect may be one of thefactors causing resistance to diet-induced obesity in the malepups with free choice of components of obesogenic diet." (PMID 34782887, 2021). "High leptin concentrations are directly associated with obesity and/or the subsequent development of metabolic disease sequelae, such as insulin resistance, type 2 diabetes, and cardiovascular diseases, all key risk factors associated with increased coronavirus disease 2019 (COVID-19) mortality." (PMID 35002761, 2021). "Therefore, chronic impairment of nutritional balance, such as undernutrition, obesity and diabetes, and alterations in leptin or kisspeptin pathways are risk factors for infertility." (PMID 33573212, 2021). "Furthermore, leptin protein was associated with obesity indicators positively and with miR-6803-3p negatively." (PMID 34440082, 2021). "Despite a different underlying molecular mechanism at the base of the leptin deficiency (ligand versus receptor), both models show a similar phenotype in regard to hyperphagia, hypometabolism, and obesity, but manifest different impairments in glucose metabolism." (PMID 34183063, 2021).
Obesity (continued). "Leptin could explain the positive correlation between obesity and an elevated risk for breast cancer, accelerated tumor progression and poorer overall prognosis." (PMID 33946741, 2021). "Effectively, obesity-associated leptin resistance may have similar effects to hypoleptinaemia on the HPG axis, with central suppression of GnRH secretion mediated through enhanced hypothalamic release of agouti-related peptide." (PMID 34360982, 2021). "In line with the promoting role of excess adiposity in carcinogenesis, a decrease in circulating levels of adiponectin and/or adiponectin/leptin ratio is associated with an increased risk of obesity-induced cancers, including breast, endometrial, prostate, hepatic, and colorectal cancers." (PMID 33535537, 2021). "Leptin resistance is the condition where diminished leptin sensitivity occurs, resulting in a defect in satiety detection despite high leptin levels, which has been linked to obesity." (PMID 34795562, 2021). "Increasing reports demonstrated that a vital risk factor for obesity is leptin resistance." (PMID 33849593, 2021). "In a large cross-sectional study with 6408 participants, comparison of leptin levels in isolated knee and isolated hand OA demonstrated that serum leptin levels were positively associated with OA and leptin mainly mediated the association of OA with obesity." (PMID 34440223, 2021). "The association of adipokines secretion with obesity is characterized by hyperleptinemia, leptin resistance, decreased adiponectin/leptin index, and hypoadiponectinemia, combined with hyperandrogenism and insulin resistance indicates the participation of these adipokines in genesis oligomenorrhea." (PMID 35126755, 2021). "GERD-independent associations between circulating leptin concentrations and the incidence of BE have been observed in a number of studies, highlighting the role of adipose inflammation in the development of BE in obesity." (PMID 33777773, 2021). "Results of these studies will enable a deeper understanding of leptin physiology and possible therapeutic applications as well as prevention of obesity and metabolic disease associated with leptin and leptin receptor heterozygosity or partial leptin deficiency." (PMID 34448070, 2021). "The results of these researches revealed that zinc deficiency in obesity further increases the production and secretion of leptin; in contrast, zinc supplementation can reduce elevated levels of leptin and can be effective in improvement of the leptin resistance which occurs following obesity." (PMID 34631042, 2021). "The effect of hypertension could also be masked by parallel changes affecting the Ad/L ratio, as there is evidence that both low levels of adiponectin and high levels of leptin may act as mediators in the development of obesity-associated hypertension." (PMID 34731089, 2021). "The βOHB and SCFAs can influence epigenetic changes in infant obese gene expression and exert potential anti-obesity and anti-inflammatory effects by targeting obesity-associated inflammation via interactions of the hypothalamic appetite-regulating hormones leptin and insulin." (PMID 34835958, 2021). "We have learned that obesity is a much more complicated condition than just the collection of fat tissue and causes a state of low-grade inflammation in which insulin resistance and increased leptin levels probably play a role." (PMID 34836093, 2021). "Obesity risk could theoretically be altered via modification of the development of leptin-mediated neuronal circuitry regulating body weight toward the defense of a lower body weight in those at risk." (PMID 34955895, 2021). "In addition, according to a recent study, leptin disrupts epithelial polarity and promotes premalignant alteration in the mammary gland, a finding that further links obesity hyperleptinemia with breast cancer risk." (PMID 33751362, 2021).
Obesity (continued). "Decreased leptin and increased ghrelin levels are related to short sleep duration, and obesity as a chronic inflammation may be associated with insufficient sleep." (PMID 34760255, 2021). "The authors of that study proposed that there is a relationship between obesity and sarcopenia associated with inflammatory conditions and suggested that leptin administration could be a beneficial therapeutic approach for preventing muscle loss." (PMID 34064680, 2021). "Besides, it was associated with a significant reduction in plasma leptin levels, a key adipokine in the development of diet-induced obesity." (PMID 34568404, 2021). "Animal studies using vascular injury mouse models have shown that elevated leptin may promote vascular remodeling and arterial stiffness associated with obesity." (PMID 34064112, 2021). "Peripheral adipose tissue and interaction of leptin with the kisspeptin system may be associated with obesity and puberty." (PMID 33643970, 2021). "Our study showed that LEP G19A polymorphism decreases cancer risk, but the exact mechanism is unknown and mounting evidence indicates that obesity may greatly increase the risk of cancer." (PMID 34868961, 2021). "Leptin resistance is a main risk factor of obesity in humans." (PMID 33849593, 2021). "Its elevated levels in obesity are proportional to body weight increase, associated with a bizarre loss of effects on the hypothalamic control of appetite, configuring a condition described as leptin resistance." (PMID 34684432, 2021). "In addition, the development of obesity which is characterized by leptin resistance has been associated with inflammation both in peripheral tissues including adipose tissue and in hypothalamic areas critical for energy homeostasis." (PMID 34556775, 2021). "We asked whether IL-33 and leptin, both expressed in the airway, might interact with each other and contribute to the pathogenesis of obesity-associated asthma." (PMID 34074279, 2021). "In addition to activating glial cells, a high-fat diet also reduced the response of ARC neurons to exogenous leptin in mice resulting in leptin resistance, a phenomenon associated with obesity." (PMID 34208079, 2021). "Aberrant insulin and leptin levels have been associated with both miscarriage and preeclampsia, both of which are increased with pregravid obesity." (PMID 34195568, 2021). "Underlying mechanisms of obesity on the severity of COVID-19 may involve abnormalities in the production of adipokines (e.g., increased leptin and decreased adiponectin) by adipose tissue." (PMID 34940517, 2021). "Currently described non-syndromic forms of mendelian obesity comprise mainly genetic defects in the leptin/melanocortin pathway, such as mutations in the genes encoding LEP, LEPR, prohormone convertase 1 (PC1/3), proopiomelanocortin (POMC) and melanocortin receptor 4 (MC4R), leading to overeating." (PMID 33800718, 2021). "Moreover, leptin is also uncovered to participate in the pathophysiology of energy metabolism, endocrine diseases, neurovascular diseases, or obesity and metabolism-associated diseases." (PMID 33799880, 2021). "Thus, enhancing Prlh-mediated neurotransmission by the NTS blocks the hyperphagia and obesity associated with leptin deficiency, increased AgRP neuron activity and/or impaired melanocortin signaling, as well as during DIO." (PMID 34462445, 2021). "Obesity is associated with higher circulating leptin levels." (PMID 33920379, 2021). "Moreover, important risk factors for obesity-associated cardiovascular diseases, including dyslipidaemia and leptin/adiponectin imbalance, have been reported in obese post-menopausal women and ovariectomized animals." (PMID 33420094, 2021). "Similarly, these same proteins showed sex differences, in particular leptin and IL-1 beta, known to be higher in females and resulting in a higher risk to develop obesity than males." (PMID 34289836, 2021).